IRF8 (interferon regulatory factor 8)
Diseases named in the same sentence as IRF8 in open-access papers (continued):
Sharing a sentence is not in itself a finding about the gene and the disease.
bacterial infections (10 papers, 2012 to 2026). "In vivo, Irf8-deficient mice are highly susceptible to bacterial infection compared with wildtype animals, confirming the critical role of IRF8 in NAIP/NLRC4 inflammasome activation." (PMID 33494299, 2021). "IRF8 is present within footprints of selection for Iraqi breeds and is linked to the acquired immune response to protozoan and bacterial infections." (PMID 34654366, 2021). "The data suggest that rhinoviral infections facilitate bacterial infections of airway epithelial cells by a cascade consisting of Stat3 activation, IRF8 upregulation, downregulation of acid ceramidase activity, and reduced sphingosine levels." (PMID 41861994, 2026). "(2018) demonstrated that Interferon Regulatory Factor 8 (IRF8) regulates the transcription of Niap genes for the optimal activation of NLRC4 upon bacterial infections." (PMID 40692785, 2025). "The expression of NAIPs and NLRC4 are regulated by the interferon regulatory factor 8 (IRF8) transcription factor during bacterial infection." (PMID 33494299, 2021). "In addition to IL-12 production, other IRF8-mediated macrophage responses to bacterial infection include autophagy and inflammasome activation." (PMID 36078039, 2022). "Additionally, IRF8 was found to protect against S. typhimurium and B. thailandensis bacterial infection in vivo likely due to inflammasome-dependent cytokines and pyroptosis." (PMID 36078039, 2022).
infectious disease (4 papers, 2015 to 2024). A disorder directly resulting from the presence and activity of a microbial, viral, or parasitic agent in humans. "A bioinformatic analysis identified 10 genes in IBM, most of them involved in immune mediated and infectious diseases, including CCR5 (encoding the human C–C motif chemokine receptor type 5), IRF8 (interferon regulatory factor 8), HLA DRB1, CD74, and others." (PMID 38693436, 2024).
kidney disease (4 papers, 2019 to 2023). "Few studies, mainly conducted in animal models, managed to prove that IRF8-deficiency could reduce kidney disease." (PMID 31507612, 2019). "Our findings indicate that a high expression of different co-DEGs was correlated with a low glomerular filtration rate in kidney disease samples (IL10RA, HLA-DPA1, r = −0.490, p < 0.001; IRF8, HLA-DRA, r = −0.500, p < 0.001; HLA-DPB1, r = −0.510, p < 0.001; HLA-DMA, r = −0.480, p < 0.001)." (PMID 34692653, 2021).
hematopoietic cancer (2 papers, 2021 to 2022). "IRF8 may also function in non-hematopoietic cancers to negatively regulate the expression of MMP3, a matrix metalloproteinase associated with a poor prognosis and metastasis in various solid organ cancers." (PMID 36078039, 2022). "IRF8 is therefore a therapeutic target in both hematopoietic and non-hematopoietic cancer." (PMID 36078039, 2022).
adenocarcinoma (1 paper, 2014). A common cancer characterized by the presence of malignant glandular cells. "IRF8 protein expression was frequently silenced in males, smokers, patients with non-adenocarcinoma or with wild-type EGFR, or in an advanced stage." (PMID 25120651, 2014). "Secondly, although based on a relatively small sample size and short-term follow up, IRF8 methylation was correlated with poorer recurrence-free survival in adenocarcinoma cases." (PMID 25120651, 2014). "IRF8 methylation correlated with recurrent prognosis in adenocarcinomas (log-rank test, P=0.048)." (PMID 25120651, 2014). "IRF8 methylation may be clinically useful, utilized as an adjuvant therapy or as a recurrence-prediction marker of adenocarcinoma." (PMID 25120651, 2014).
brain disorder (1 paper, 2024). A disease affecting the brain or part of the brain. "We found 7 variants that were associated with neurodevelopment and brain disorders, of which, 4 variants were found in both patients, namely in genes CTBP2, CDC27, UNC13D and IRF8, and 3 variants found in either of the patients, NDUFAF3, MRPS25, MORC3." (PMID 38638145, 2024).
hematological malignancies (1 paper, 2022). "Transcription factors activated in both liver and muscle include Irf8, Jun, Egr1, Cebpa, Foxl2, the hypoxia-inducible factor Hif1a, and Runx1, a key regulator in hematological malignancies." (PMID 35865523, 2022).
metabolic disorder (1 paper, 2025). "In summary, IRF8 knockdown reduces hepatic lipid accumulation and alleviates metabolic disorders induced by an HFD." (PMID 40083324, 2025).
IRF8 also shares sentences with these, for which no sentence is quoted: acute kidney injury (3 papers); multiple myeloma (3); acute promyelocytic leukemia (2); brain tumor (2); cardiovascular disease (2); chronic granulomatous disease (2); diffuse large B-cell lymphoma (2); follicle center lymphoma (2); genetic disorders (2); hypertrophic cardiomyopathy (2); liver cancer (2); metabolic syndrome (2); monocytopenia (2); myelo-proliferative disorder (2); neurodegenerative disease (2); periodontal disease (2); psoriasis (2); Stroke (2); Thrombocytopenia (2); Thrombocytosis (2); thrombosis (2); age-related macular degeneration (1); airway allergy (1); amyotrophic lateral sclerosis (1); anaplastic oligoastrocytoma (1); anemia (1); ankylosing spondylitis (1); astrocytoma (1); atrial fibrillation (1); B-cell acute lymphoblastic leukemia (1).
A further 68 diseases each share a sentence with IRF8 in 1 paper.